HSD11B2 (hydroxysteroid 11-beta dehydrogenase 2)
Diseases named in the same sentence as HSD11B2 in open-access papers (continued):
Sharing a sentence is not in itself a finding about the gene and the disease.
HSD11B2 also shares sentences with these, for which no sentence is quoted: apparent mineralocorticoid excess (5 papers); melanoma (3); colon cancer (2); Insulin resistance (2); metabolic syndrome (2); acute respiratory distress syndrome (1); atherosclerosis (1); blood pressure (1); cardiac hypertrophy (1); cerebral palsy (1); Cushing syndrome (1); cystic fibrosis (1); gastrointestinal stromal tumor (1); hepatoma (1); Hyperinsulinemia (1); hypertriglyceridemia (1); hypocortisolemia (1); Impaired glucose tolerance (1); ischemia (1); malnutrition (1); mood disorder (1); neurodevelopmental disorder (1); osteoporosis (1); Pendred syndrome (1); placental insufficiency (1); Polydipsia (1); Polyuria (1); pregnancy hypertension (1); psychiatric disorder (1); renal tubular dysfunctions (1).
A further 1 disease shares a sentence with HSD11B2 in 1 paper.